BRAF (B-Raf proto-oncogene, serine/threonine kinase)
Diseases named in the same sentence as BRAF in open-access papers (continued):
Sharing a sentence is not in itself a finding about the gene and the disease.
cutaneous melanoma (continued). "This deferred selection for MAP-kinase pathway mutations results in an unexpected heterogeneity in the primary tumors, with BRAF V600E mutation or NRAS Q61 mutations present in some areas of the tumor and absent in others, a finding that is highly unusual for cutaneous melanomas." (PMID 39034322, 2024). "Furthermore, whereas 42–45% of primary cutaneous melanomas carry a BRAF V600E mutation and are therefore predicted to respond to targeted BRAF-/MEK inhibition, UM do not carry BRAF V600E mutations." (PMID 35681616, 2022). "In contrast to BRAF driver mutations, KIT driver mutations are present to a higher extent in acral and mucosal melanomas (10.8% and 11.5% respectively) compared to cutaneous melanomas (9.7% in CSD and 5.1% in non-CSD cutaneous melanoma)." (PMID 36276131, 2022). "However, the relationship between UVR and cutaneous melanoma is not yet fully understood, given the absence of a UV DNA damage signature in genes relevant to cutaneous melanoma such as BRAF, NRAS, or CDKN2A (cyclin dependent kinase inhibitor 2A)." (PMID 35682684, 2022). "The NCCN panel does not recommend BRAF testing for resected pathologic stage I or II cutaneous melanoma unless the results may be used to direct participation in clinical trials." (PMID 34068774, 2021). "Mutations in BRAF and NRAS are not so uncommon among mucosal melanomas (up to 20% of cases); rather, they have peculiar features that are radically different from those observed in cutaneous melanomas." (PMID 35008570, 2021). "However, BRAF or NRAS mutations, which mediate sensitivity to the BRAF inhibitors vemurafenib and dabrafenib in cutaneous melanoma, are not common in UM." (PMID 32726977, 2020). "BRAF and NRAS mutations, frequently occurring in cutaneous melanoma, do not occur in posterior UM." (PMID 32718045, 2020). "All the 11 samples in the BRAF group were observed in non-CSD cutaneous melanomas (11/18, 61%)." (PMID 32083130, 2020). "Most studies put forward that unlike human cutaneous melanomas, human and canine mucosal melanomas are more often associated with high copy number alterations, lower TMB, and structural variation burden rather than the high specific hotspot gene mutations (BRAF or NRAS) seen in cutaneous humans." (PMID 39408717, 2024). "Therefore, BRAF inhibitors frequently used in skin melanoma do not work in UM." (PMID 34753889, 2022). "The genetic abnormalities commonly associated with these two subtypes of cutaneous melanoma are neurofibromin 1 (NF1), NRAS, BRAF non-V600E mutations, or KIT in CSID, while non-CSID is associated with BRAF V600E mutations, suggesting that the non-CSID might originate from nevi." (PMID 33256089, 2020). "A relevant finding of our series was that nearly half of patients diagnosed with advanced cutaneous melanoma (stages III and IV) did not undergo BRAF testing." (PMID 40994966, 2025). "In panel B, we show the oncoprint report for retrieval in which we inquired for co-occurrence of genomic alterations in BRAF, N-RAS and c-KIT genes in 278 total cases of skin cutaneous melanoma analyzed by TCGA provisional study (not published)." (PMID 27746730, 2016). "However, our mutation analysis showed that the mutation rate of BRAF was less than 2.5% in ocular melanomas (UVM), indicating that BRAF mutation may have little to do with the development of UVM and our proposed prognostic signature does not apply for non-cutaneous melanoma." (PMID 37205993, 2023).
colon carcinoma (562 papers, 2003 to 2026). "The combination of MK-5108 and trametinib showed synergistic enhancements of antitumor effect in three colon cancer cell lines harboring KRAS or BRAF mutation." (PMID 40546348, 2025). "Here, we used aggressive colon cancer patient-derived organoids (PDO) with co-occurring mutations in BRAF (V600E) and RNF43 (P441fs)." (PMID 40687798, 2025). "Examination of the intracellular functions of PD-L1 has found that PD-L1 is highly expressed in both the cytoplasm and nucleus of BRAF-mutated colon cancer cells and tissues." (PMID 40747299, 2025). "For example, left-half colon cancer has high expression of epiregulin (EREG) and amphiregulin (AREG) proteins, while right-half colon cancer has high mutation rates of the TGFbR2 and BRAF genes." (PMID 41182556, 2025). "While cancers with BRAF V600E mutations respond well to cetuximab + encorafenib in the metastatic setting, its impact in early-stage colon cancer needs to be established as new trials are testing encorafenib-based treatments in this population." (PMID 41294686, 2025). "We conducted a systematic review and meta-analysis of six randomized controlled trials involving 6836 patients with BRAF wild-type and 843 patients with BRAF V600E mutations in stage 2–3 colon cancer." (PMID 41294686, 2025). "In colon cancer cell lines harboring BRAF V600E mutations, EGFR re-activates MAPK conferring resistance to BRAF inhibition with vemurafenib." (PMID 40869231, 2025). "In colon cancer, for example, a BRAF V600E mutation in approximately 10% of patients is associated with a poor prognosis." (PMID 40869231, 2025). "This study found that BRAF V600E-mutated rectal cancer had a worse prognosis than left-sided colon cancer." (PMID 39464719, 2024). "In this study, it was found that the prognosis of right-sided colon cancers with BRAF V600E mutations was worse than that of left-sided colon cancers." (PMID 39464719, 2024). "This systematic review focuses on the prognostic significance of KRAS, NRAS, and BRAF mutations within MSI-H colon cancer." (PMID 38786299, 2024). "Another report pinpointed to the association of CDX2 suppression with right colon cancers and BRAF mutations." (PMID 39452477, 2024). "Human colon cancers driven by BRAF mutation, predominantly occurring in the proximal colon, tend to occur in the context of CDX2 downregulation by epigenetic silencing." (PMID 38360902, 2024). "This has been observed previously; for example, BRAF mutation is a predictor of dabrafenib monotherapy activity in multiple cancer types and of response to dabrafenib-containing combinations in colon cancer." (PMID 38456804, 2024). "Our findings confirm the complex interplay between genetic mutations and MSI status, emphasizing the nuanced role of MSI in modifying the prognostic implications of KRAS, NRAS, and BRAF mutations in colon cancer." (PMID 38786299, 2024). "BRAF mutation is predominant in proximal colon cancers in the context of CIMP-H and with a tendency to be mutually exclusive of APC mutations." (PMID 38360902, 2024). "The pooled analysis of seven trials within the ACCENT/IDEA consortium explores the distinct prognostic implications of KRAS exon 2 submutations and the BRAF V600E mutation in stage III colon cancer." (PMID 38786299, 2024). "The BRAF mutation, (primarily caused by a missense mutation at V600E) was a significant mutation in colon cancers." (PMID 38327746, 2024). "BRAFV600E poorly initiates colon cancer in mice due to oncogenic BRAF-induced tissue differentiation and loss of intestinal stem cells." (PMID 36778401, 2024).
colon carcinoma (continued). "This study specifically focused on the distribution of the mutation frequency of KRAS and BRAF genes across different clusters, which were important for targeted therapy in patients with colon cancer." (PMID 38327746, 2024). "Some studies assessed the feasibility of IHC instead of PCR to detect the mutated BRAF and reported near-to-complete concordance between both techniques in various cancers, including colon carcinomas." (PMID 36673047, 2023). "In fact, right colon cancer is associated more often with microsatellite instability (MSI), BRAF mutations, and CpG islet methylation, while left colon cancer more frequently presents chromosomal instability." (PMID 36765761, 2023). "BRAF mutations were present in three models: V600E in colon cancer RKO, COLO 205, and G464V in mammary cancer MDA-MB-231 cells." (PMID 37830744, 2023). "One such mutation is the BRAF mutation, which has been found to be more common in right-sided colon cancers compared to left-sided colon cancers." (PMID 37629285, 2023). "Based on this in silico finding, we propose that reduced level of secreted HSPA5/GRP78 should be further investigated as a potential indicator of treatment outcomes in BRAF-mutated colon cancer." (PMID 37106808, 2023). "We also lacked data on tumor sidedness; prior literature has shown that RAS, KRAS, and BRAF mutations occur more frequently among right‐sided colon tumors than left‐sided colon tumors." (PMID 35837788, 2023). "The most frequent BRAF variant was Val600Glu (V600E), which occurred in 72 samples; 10.4% of all patients had colon cancer." (PMID 37483495, 2023). "Altogether, aberrant regulation of DNA replication has emerged as an important upregulated secretory feature linked with vemurafenib resistance in BRAF-mutated colon cancer cells." (PMID 37106808, 2023). "As for MAPK genes, colonic tumors with BRAF mutations, versus wild‐type tumors, are more likely to be located in the right colon and either be poorly differentiated or be a mucinous adenocarcinoma." (PMID 36734304, 2023). "Serrated colon cancers are commonly associated with the BRAF-V600E mutant allele as the truncal mutation." (PMID 38136364, 2023). "A systematic review of nine randomized controlled phase III trials has revealed that KRAS and BRAF mutations are possible predictors of poor prognosis for stage II/III colon cancer treated with adjuvant chemotherapy." (PMID 37784019, 2023). "The major secretome features associated with acquired resistance to vemurafenib in BRAF-mutated colon cancer cells revealed in this study included deregulation of DNA replication and ER function." (PMID 37106808, 2023). "For BRAF (V600E) mutated colon cancer, vemurafenib feedback activates EGFR, although it can inhibit BRAF (V600E)." (PMID 36678567, 2023). "Regarding the primary tumor location, the BRAF V600E mutation was more commonly seen in right‐side colon cancer (54.2%), while left‐side and rectal tumors were observed in 24.4% and 21.3% of patients, respectively." (PMID 36912150, 2023). "A375 and BRAF-mutated colon cancer COLO 205 cells were treated with tunlametinib, AZD6244, and GSK212 for 48 h to evaluate the effect on cell apoptosis." (PMID 37808191, 2023). "Further analysis revealed that reduced tumor growth mediated by specific silencing of the convertase Furin in KRAS or BRAF mutated-induced colon tumors was associated with reduced expression of LGR5 and NANOG compared to wild-type KRAS and BRAF tumors." (PMID 35267511, 2022). "The activating BRAF p.Val600Glu (p.V600E) variant is commonly seen in sporadic colorectal tumors and rarely reported in LS-related colon cancers." (PMID 36091175, 2022). "Of all BRAF mutations, the BRAF V600E mutation accounts for the majority (approximately 90%) in colon cancer." (PMID 35323316, 2022). "Given that, in BRAF mutated colon cancer, the combination of BRAF inhibitors with anti-EGFR agents is a promising strategy." (PMID 36686797, 2022).
colon carcinoma (continued). "Taken together, our findings indicate that PCs play an important role in the malignant phenotype of colon CSCs and stem cell markers’ expression and highlight PCs repression, particularly of Furin, to target colon tumors with KRAS or BRAF mutation." (PMID 35267511, 2022). "The density of TILs is frequently high in MSI-H tumors, in right-sided colon tumors, and in tumors that harbor a BRAF mutation." (PMID 36505147, 2022). "Given that, in BRAF mutated colon cancer, and glioma the combination of BRAF inhibitors with anti-EGFR agents is a promising strategy." (PMID 36686797, 2022). "It is well known that BRAF mutations usually accompany sporadic microsatellite instability-high (MSI-H) colon cancers." (PMID 35592200, 2022). "Microsatellite instability-high (MSI-H), deficiency of mismatch repair genes, KRAS and BRAF mutations, and CpG island methylation are more common in right colon cancer than that in left colon cancer." (PMID 35143566, 2022). "Weaker associations were found between right colon tumors and other mutations, such as BRAF mutations OR = 1.939 (95% CI = [0.562, 6.698]) and RR2= 1.563 (95% CI = [1.209, 1.915]), and EGFR mutations, RR2 = 1.424 (95% CI = [1.314, 1.534])." (PMID 35681771, 2022). "Those that show significant changes are ATP2B4, which was downregulated in all the Furin-silenced colon cancer cells, and the P2Y receptor, which was specifically repressed in BRAF mutated colon cancer cells." (PMID 35267511, 2022). "We also identified the implication of the PCs in several markers of stemness and calcium regulators in colon cancer cells with KRAS or BRAF mutation." (PMID 35267511, 2022). "Assuming the high prevalence, in stage II and III, of microsatellite instability (MSI) in KRAS-mutated colon cancer, the evaluation of both BRAF and KRAS mutations in MSI colon cancers is useful for prognosis." (PMID 35456940, 2022). "The study included 180 colon cancer patients: 120 patients with wild-type BRAF protein and 60 patients in the propensities-matched BRAF mutation group." (PMID 35454158, 2022). "Given that KRAS and BRAF mutations are generally mutually exclusive, genetic alterations of KRAS and BRAF were likely to occur in different colon tumors, implying that right-sided colon tumors are predisposed to harbor KRAS-BRAF pathway mutations." (PMID 36439454, 2022). "More than 90% of precancerous lesions in the colon involve either mutations to the APC or BRAF genes; drugs capable of specifically killing cells with these mutations should be useful for reducing the incidence of colon cancer." (PMID 36860494, 2022). "For example, the expression of ATP2B4, a Plasma membrane Ca2+ ATPases (PMCAs) known as the major ATP-consuming pumps responsible for Ca2+ extrusion from the cells, is repressed in colon cancer with mutated or WT KRAS or BRAF." (PMID 35267511, 2022). "Intriguingly, these two studies also found that BRAF mutational frequency was significantly higher in right-sided colon cancers than in left-sided colon cancers." (PMID 36439454, 2022). "In colon carcinoma, for example, BRAF V600E inhibition has been shown to cause a rapid feedback activation of EGFR, which supports continued proliferation in the presence of BRAF V600E inhibition." (PMID 34630336, 2021). "As expected, a subset of mutations cluster to specific loci in the MSI colon cancer exome, similar to the well documented BRAF SNP at chr7:140753336, it seems probable that the most prevalent mutations also play a role in tumorigenesis." (PMID 34181673, 2021). "Here, we describe a mouse model of right-sided colon cancer driven by oncogenic BRAF and loss of epithelial TGFβ-receptor signalling." (PMID 34103493, 2021).
colon carcinoma (continued). "Our data demonstrated the interaction between NOX1 and BRAF mutation plays an important role in colon cancer." (PMID 34073365, 2021). "BRAF mutated colon cancer presents with poor survival, and the treatment strategies are controversial." (PMID 34381786, 2021). "The finding of increased expression and activity of NPM1 in BRAF-mutated colon cancer prompted us to examine its potential role in modulating the response and resistance to BRAFV600E inhibitor vemurafenib." (PMID 34201061, 2021). "Previous studies mainly focused on identifying characteristic gene expression patterns of BRAFV600E-mutated colon cancer by examining differences between oncogenic BRAF vs. either the KRAS mutation or double wild-type BRAF/KRAS." (PMID 34201061, 2021). "In conclusion, our study demonstrates a different pattern of the immune microenvironment in BRAF mutated colon cancer and provides insights into the future use of checkpoint inhibitors in this subgroup of patients." (PMID 34381786, 2021). "We observed a trend towards an increased basal expression of the NPM1 protein in BRAF-mutated colon cancer cell lines in comparison with the cells carrying either WT BRAF/mutant KRAS or double WT BRAF/KRAS." (PMID 34201061, 2021). "Here the authors develop a mouse model of rCRC that recapitulates human BRAF-mutant rCRC and show that loss of TGFβ-receptor signalling and inflammation induce the development of colonic tumours with a foetal-like phenotype." (PMID 34103493, 2021). "In conclusion, the present study provides insights into the tumor microenvironment in BRAF mutated colon cancer and discussed potential therapeutic targets from the perspective of immune biology." (PMID 34381786, 2021). "In patients from the GEO dataset, BRAF mutation colon cancer also had higher expressions of CTLA-4 (p = 0.031) and LAG-3 (p = 0.0011), but had no significant expression of PD-1 (p = 0.58)." (PMID 34381786, 2021). "Results reveal an improved response by combinatorial treatment in some defined molecular subgroups and potential alternative treatment options in KRAS- and BRAF-mutated colon cancer." (PMID 34885128, 2021). "Findings from this study point to the therapeutic potential of targeting the NPM1/c-Myc axis in BRAF-mutated colon cancer and provide a framework to devise novel strategies for counteracting the resistance to BRAF inhibition in colon cancer." (PMID 34201061, 2021). "In the present study, we pooled The Cancer Genome Atlas (TCGA) and Gene Expression Omnibus (GEO) datasets to explore the immune landscape of BRAF mutated colon cancer and to validate the important immune markers in patient specimens." (PMID 34381786, 2021). "For NMAC, patients with right-sided colon tumors had more BRAF mutations than patients with left-sided colon tumors or patients with rectal tumors." (PMID 33738258, 2021). "BRAF mutation was an independent factor of recurrence in microsatellite-stabilized colon cancer, and the outcome of CC patients with BRAF gene mutations was significantly poor." (PMID 34610581, 2021). "The literature has reported that BRAF mutated colon cancer patients had a much poorer survival rate that wild-type patients, we therefore analyzed overall survival in the two cohorts." (PMID 34381786, 2021). "Here, we describe a mouse model of serrated intestinal cancer wherein oncogenic BRAF and loss of epithelial TGFβ-receptor cooperatively promote the formation of right-sided colonic tumours with a Wnt-low, foetal-like signature." (PMID 34103493, 2021). "Through assessment of immune scores, we identified that BRAF mutated colon cancer had more stromal cells, more immune cell infiltration, and lower tumor purity in tumor tissue." (PMID 34381786, 2021). "Hight al. reported on the potential of the peptide-based 18F-FB-VAD-fluormethylketone caspase 3 substrate to visualize apoptosis-induction in (V600E)BRAF colon cancer xenografts in mice using a combined BRAF-mutation inhibitor and a dual P13K/mTor inhibitor." (PMID 33803180, 2021).